EPHA2 (EPH receptor A2)
Diseases named in the same sentence as EPHA2 in open-access papers (continued):
Sharing a sentence is not in itself a finding about the gene and the disease.
tumor (continued). "Some Eph receptors, especially EphA2, attract increasing attention because of demonstrated or hypothesized contributions to modulatory processes controlling carcinogenesis and tumor progression." (PMID 32811512, 2020). "However, 1C1 does not demonstrate direct cytotoxicity and antitumor effects, but allows highly toxic chemotherapeutics to be directly and specifically delivered to EphA2-expressing tumor cells." (PMID 32811512, 2020). "Moreover, remarkable tumor growth inhibition was found with simultaneous administration of EphA2-siRNA-DOPC and paclitaxel." (PMID 33003468, 2020). "Notably, LJH685 alone and combined with cisplatin increased tumor‐suppressive EphA2‐pY588 in OVCAR4 and OVCAR8, i.e., the cells effectively sensitized to platinum." (PMID 32115889, 2020). "In addition, we constructed a model of metastatic tumor in vivo via nude mouse tail vein injection of EphA2 knockdown 786-O-R cells." (PMID 32814829, 2020). "Moreover, we found EPHA2 was in the upstream of the PI3K/AKT signaling, and the tumor initiating role of EPHA2 has been indicated in BCa." (PMID 33087088, 2020). "Finally, Eph-DC immunizations were more effective against rechallenged tumor, consistent with their superior capacity to elicite EphA2-specific CTLs." (PMID 32811512, 2020). "The levels of EphA2 expression was also significantly correlated with tumor stage." (PMID 32795296, 2020). "Therefore, rather than broad MEK‐ERK1/2 pathway inhibition or EphA2 knockdown, the specific RSK‐EphA2‐pS897 blockade and consequent reversal to tumor‐suppressive EphA2‐pY588 correlated with the effective OC cell elimination and sensitization to platinum." (PMID 32115889, 2020). "Since the antibody binds both mouse as well as human EphA2, specificity for EphA2 in the tumor compared to normal tissues could also be assessed in mice." (PMID 32397088, 2020). "Based on earlier findings, EphA2 can play either a tumor-promoting or tumor-suppressive role, and it may adopt two different mechanisms to exert its effects on cancer biology, involving a ligand-dependent or ligand-independent pathway." (PMID 32203105, 2020). "Specifically, EphA2 and EphA3 have been shown to be expressed individually in 60% of GBM patients, including in regions of tumor neovasculature, tumor-associated immune cells, and tumor-infiltrating cells." (PMID 32340173, 2020). "Consistent with the other models, EphA2-ILs-DTXp at 59 mg/kg led to significant tumor regression with extended survival when compared with an equitoxic dose of free DTX at 10 mg/kg (ANOVA and post-hoc Tukey HSD; p < 0.05; Log-Rank Prob > ChiSq Survival: p < 0.05)." (PMID 33092175, 2020). "Tumor-suppressive factor directly down-regulated by TECs via paracrine EphA2 signaling." (PMID 32974337, 2020). "The concordant expression extends to tumor-associated vasculature, where there was concordant expression in 9 out of 10 samples, with one metastatic sample lacking EphA2 expression on the vasculature." (PMID 33092175, 2020). "Mechanistically, pharmacological inhibition or knockdown of RSK1/2 prevented oncogenic EphA2‐S897 phosphorylation and EphA2‐GPRC5A co‐regulation, thereby facilitating a signaling shift to the canonical tumor‐suppressive tyrosine phosphorylation and consequent downregulation of EphA2." (PMID 32115889, 2020). "So, among the network we constructed, we wonder if the interaction between EphA2 and miR‐26b could play roles in tumour angiogenesis and proliferation in BC." (PMID 32233022, 2020). "However, subsequent generation of a bsAb against EphA2 and EphA3 showed that even unconjugated antibody was effective in reducing stem cell clonogenicity in vitro, and tumor burden of recurrent GBM xenografts in vivo." (PMID 32397088, 2020). "Moreover, in the peritoneal injection model, EPHA2 knockdown significantly decreased the number of MKN45 tumor nodules and total tumor weights in the peritoneal cavity of NOD/SCID mice." (PMID 32005975, 2020).
tumor (continued). "Interestingly, generation of a tri-cistronic transgene encoding three CAR molecules against HER2, EphA2 and IL13Rα2, dubbed universal CAR-T (UCAR), was shown to overcome interpatient heterogeneity and target 100% of tumor cells." (PMID 33154756, 2020). "In our HGSC cell cultures and ex vivo models, pharmacological RSK inhibition blocked the activation of the tumor‐promoting EphA2 activity, which in turn led to enhanced canonical tumor‐suppressive EphA2‐pY588 signaling, coincidentally sensitizing the cells to platinum‐induced apoptosis." (PMID 32115889, 2020). "Indeed, tumor cells infected with EphA2-TEA-VV induced T cell activation, as evidenced by interferon-γ and interleukin-2 secretion." (PMID 32664210, 2020). "EPHA2mutation was present in LUSC, and it could increase tumor invasion and survival by activating thefocal adhesions and actin cytoskeletal regulatory proteins, indicating EPHA2 as apotential therapeutic target of LUSC, which was consistent with our findings." (PMID 33196759, 2020). "We detected the leakage of erythrocytes (asterisks) through the intercellular gap of the endothelial cells (red arrow) and assumed the drained erythrocytes to enter the interstitial space, surrounded by the EphA2-expressing large cuboidal tumor cells (blue arrows)." (PMID 30833656, 2019). "Furthermore, HSP90 inhibitor 17-MAG has been indicated as an immune adjuvant in the context of vaccines targeting HSP90 client protein EphA2, reconditioning the tumor microenvironment to enhance patient immune responses." (PMID 31878360, 2019). "Although weak EphA2 expression was detected in the endothelial cells, we could identify VM channels, lined by large cuboidal tumor cells with strong EphA2 expression." (PMID 30833656, 2019). "VM is positively correlated with high expression levels of EphA2, suggesting that EphA2 signaling may be involved in the promotion of tumor metastasis by VM formation during gastric tumorigenesis." (PMID 30833656, 2019). "Due to the prominent tumour role of EPHA2 in CRC, this mechanism could be involved in SOCS2 antitumour activity in CRC." (PMID 31091767, 2019). "As examples of markers expressed by CD123+ DCs, targeting EPHA2 may produce anti-tumor effects, while blocking of IL28RA result in augmented vaccine responses." (PMID 29795118, 2018). "Treatment with UniPR1331 reduced EphA2 immunostaining to about 20% of tumor area (SI score=4)." (PMID 29849945, 2018). "A tumor grade specific increase in EphA2 protein has also been observed." (PMID 29682554, 2018). "Analysis of tumor lysates revealed that EphA2 protein levels decreased upon ALW treatment." (PMID 30451837, 2018). "More importantly, we also discovered that the crosstalk could bi-directionally activate EPHA2 in both tumor cell and CAFs, suggesting the direct physical interaction between CAFs and MDA-MB-231 cells." (PMID 29946230, 2018). "Briefly, EphA2 is functionally vital to tumor growth and development." (PMID 29861465, 2018). "Additionally, Eph/ephrin signaling has been suggested to be a controlling factor in vasculomimicry (VM) and tumor angiogenesis where EphA2 emerged as a pivotal driver." (PMID 29849945, 2018). "Restoration of miR-502d-3p decreased EphA2 expression levels and suppressed tumor growth." (PMID 29755664, 2018). "In addition to EGFRvIII, EphA2, IL-13Ra2, and HER2, several other tumor-associated antigens have previously been explored as targets for GBM therapies in preclinical models." (PMID 30740109, 2018). "MiR-502d-3p is a tumor suppressor, negatively regulating EphA2." (PMID 29755664, 2018). "In addition to being highly expressed in GBM tumour cells, EphA2 expression has also been correlated with the subpopulation of GSC regarding their propagating ability and pool size." (PMID 30914876, 2018). "It has also been suggested that EphA2 contributes to the malignant transformation of tumours." (PMID 30914876, 2018).
tumor (continued). "Hence, the contextual presence of ligand dramatically influences the ability of EphA2 to elicit cell adhesive or repulsive forces to impact the behavior of tumor cells." (PMID 29290990, 2017). "Interestingly, EphA2 overexpression is also correlated with amoeboid invasion, whereby tumor cells exhibit enhanced morphological plasticity to enable cellular deformation and passage through spatially restrictive spaces." (PMID 29290990, 2017). "Whether a protein target like EphA2 or EphB4 is suitable for image-guided oncologic surgery (IGOS) is determined by its expression pattern in the tumor in comparison with the surrounding normal tissue." (PMID 28165374, 2017). "EphA2 is a protein tyrosine kinase whose phosphorylation and activity depend on the binding of ephrin-A1, although it has been reported that EphA2 can also be constitutively active in some tumor cells." (PMID 28320399, 2017). "Moreover, both tumor growth and angiogenesis were inhibited in vivo using soluble EphA2-Fc and EphA3-Fc constructs." (PMID 28415715, 2017). "A total of 168 tumor/normal pairs were suitable for evaluation of both EphA2 and EphB4." (PMID 28165374, 2017). "EphA2 is overexpressed in tumor cells, tumor-initiating cells, and in tumor neovasculature." (PMID 27494882, 2016). "EphA2 of the A type Eph subclass is expressed at low levels in differentiated tissues but expression frequently increases in advanced cancers, implicating EphA2 in tumor progression." (PMID 27246245, 2016). "Notably, staining of serial sections revealed that TF and EphA2 positivity appeared to be concentrated to clusters of tumor cells close to necrotic areas or small clusters of budding tumor cells invading through the stroma." (PMID 27246245, 2016). "This again suggests that the targeted delivery approach may result in an accumulation of the drug in the EphA2 expressing tumor cells." (PMID 26959746, 2016). "Indeed, CT26 cells expressing EphA2-specific shRNAs show reduced Erk activity, reduced colony-forming ability in soft agar and reduced tumour growth on transplantation into syngenic Balb/c mice." (PMID 27619642, 2016). "The results suggest that the expression of EphA3, EphA2, eA1, and eA5 in cells in culture differ from their expression in tumor specimens pointing to an elevated and more frequent expression of the receptors in cells than tumors and the opposite true for the ligands." (PMID 27494882, 2016). "The EphA2 has been reported to have a higher expression in NSCLC tumors than in normal surrounding non-tumor tissue in a large fraction of cases and EphA2 expression has been associated with poor prognosis/risk for metastasis in this tumor malignancy." (PMID 27533087, 2016). "Similar to what previously found using LC/MS analysis, we observed increased fluorescence in the tumor site in mice bearing PC3 xenografts compared to mice that received a scrambled-NIR conjugate further supporting that the proposed targeting agents can direct the payload at EphA2 rich tumor sites." (PMID 26959746, 2016). "Additionally, increased EphA2 expression can promote tumor progression by inducing cancer cell growth and invasion while concurrently decreasing apoptosis." (PMID 26177500, 2015). "In addition to EphA2, many other RTKs are overexpressed in tumour tissues and involved in oncogenesis and acquired resistance to molecular-targeted agents." (PMID 26158630, 2015). "Our results indicate, that EphA2 may not only have an important role in the delamination of cancer cells from the primary tumor but also in the process of metastasis formation." (PMID 25644492, 2015). "It has been well-known that the ephrin type-A receptor 2 (EphA2), a member of the ephrin family of receptor tyrosine kinases, is overexpressed in various cancer cell types and plays an important role in tumor growth, invasiveness, angiogenesis, and metastasis through the EphA2 signaling pathway." (PMID 25788424, 2015).
tumor (continued). "However, tumor-derived Ephrin-A1 ligand can also have pro-oncogenic effects by promoting tumor angiogenesis through the stimulation of EphA2 signaling on endothelial cells." (PMID 24890385, 2014). "However, the EphA2 mRNA level was still significantly higher than that detected in the original tumour (P < 0.05)." (PMID 25788865, 2014). "The analysis of EphA2 expression in tumor tissues may aid in the identification of the patient subgroup that are at a high risk of a poor disease outcome, thereby assisting in refining therapeutic decisions for RCC patients." (PMID 25013485, 2014). "Moreover, iHsp90s are functionally compatible with T cell anti-tumor immunity, and in murine models of tumors have shown efficacy in EphA2-directed therapy." (PMID 25503774, 2014). "Certain studies have hypothesized that the high EphA2 expression level in tumor cells is due to increased protein stability." (PMID 25013485, 2014). "A high expression level of EphA2 in the cancer cells was observed in 42 tumor samples (67.7%)." (PMID 25013485, 2014). "The analysis of the expression levels of EphA2 in tumor tissues may aid in the identification of the patient subgroup that are at a high risk of a poor disease outcome." (PMID 25013485, 2014). "EPHA2 is overexpressed in tumor cells and in tumor blood vessels in different types of cancer." (PMID 25193853, 2014). "We next investigated whether EphA2-targeted Ads result in increased transduction not only in monolayer tumor cell cultures and tumor cell xenografts, but also in freshly biopsied tumor material from patients." (PMID 24760010, 2014). "Tumor reduction was achieved in a dose-dependent manner with histological analysis indicating extensive necrosis and essentially complete tumor eradication based on elimination of EphA2 staining." (PMID 24346635, 2014). "Combined expression of SRC kinase, ANXA1, CAV-1 and EphA2 was found in 31 % of tumour samples." (PMID 25594008, 2014). "Although morphological changes of U-251 cells were observed under CM stimulation, further functional experiments are still necessary to demonstrate whether hypoxia-induced soluble ephrin-A1 can induce EphA2 phosphorylation or even tumor angiogenesis." (PMID 24040255, 2013). "Our previous study showed that over-expressed EphA2 may contribute to tumor angiogenesis and have prognostic value in tongue carcinoma." (PMID 24040255, 2013). "Therefore, EphA2 agonists most likely enhance tumor suppressor signaling pathways and receptor degradation in cancer cells, but promote tumour angiogenesis." (PMID 23738943, 2013). "On the other hand, expression of EphA2 and ephrinA1 has been confirmed in both the vasculature and tumor cells in cancer tissues, and EphA2 might be required for angiogenesis in an in vitro model." (PMID 23738943, 2013). "Indeed, EphA2 is highly expressed in several kinds of tumor, and this enhanced expression is thought to be related to tumor progression." (PMID 24403271, 2013). "Such agonists may not only sever the pro-oncogenic Akt-EphA2 crosstalk, but also re-activate intrinsic ligand-dependent tumor suppressor functions of EphA2." (PMID 22916121, 2012). "However, EphA2 can also act as a tumor suppressor, and recently, high expression of both EphA2 and ephrin-A1 was found to be related to favorable prognostic factors in stage I NSCLC patients." (PMID 22853000, 2012). "In the present study we hypothesized that EphA2 signaling modulates claudin-2 gene expression via induction of cdx-2, a tumor suppressor gene in NSCLC cells." (PMID 22824143, 2012). "Importantly, ligand stimulation of tumor cells in vitro inactivates Akt and causes dephosphorylation of EphA2 on S897, pointing to the intricate dichotomy of EphA2 functions, i.e., ligand-dependent tumor suppression and ligand-independent tumor promotion." (PMID 22916121, 2012). "Moreover, silencing the expression of receptor EphA2 by siRNA significantly reduced claudin-2 expression and decreased cell proliferation and tumor formation." (PMID 22824143, 2012).
tumor (continued). "We conclude that receptor EphA2 activation by ephrin-A1 induces tumor suppressor gene cdx-2 expression which attenuates cell proliferation, tumor growth and thus may be a promising therapeutic target against NSCLC." (PMID 22824143, 2012). "In both situations, provision of exogenous agonists acting in trans could still activate EphA2, unleashing its intrinsic tumor suppressor functions to inhibit tumor cell migration and invasion." (PMID 22916121, 2012). "We stained duplicate slides with anti-ephrin-A1 or anti-EphA2 antibodies that were validated using mammary tissue from genetic deletion mouse models and quantified the percent positive tumor epithelium and relative staining intensity using a computer-based Ariol platform." (PMID 21935409, 2011). "In addition, the role of A-class Eph receptors was analyzed and inhibition of tumor angiogenesis and suppressed tumor growth in vivo was demonstrated for soluble EphA2-Fc and EphA3-Fc receptors." (PMID 20224755, 2010). "While these results demonstrate reduced tumor growth and limited metastatic spread, effectiveness of these treatments may depend upon tumor type and whether a particular tumor is dependent on EphA2-mediated pathways." (PMID 20064265, 2010). "Similarly, recent studies showed the effectiveness of soluble EphA2-Fc receptor in inhibiting tumor angiogenesis in a xenograft model of human pancreatic carcinoma." (PMID 20130824, 2009). "Total level of EphA2 expression in tumor lysates was evaluated by Western blot analysis." (PMID 20130824, 2009). "However, despite the strong correlation of EphA2 receptor expression with malignant phenotypes, the mechanism by which EphA2 contributes to tumor cell malignancy is far from clear." (PMID 20130824, 2009). "In vivo treatment with IgG25 determined the reduction of the EphA2 protein levels in the tumor and the phosphorylation of FAK on Tyr576 while administration of IgG28 caused a decrease in tumor vascularization as measured by immunohistochemical analysis of CD31 in tumor sections." (PMID 20130824, 2009). "The highest levels of EphA2, for example, are present on the most invasive tumor cells." (PMID 18648668, 2008). "However, despite the strong correlation of EphA2 receptor expression with malignant phenotypes, the mechanisms by which EphA2 contributes to tumour cell malignancy are far from clear." (PMID 18797457, 2008). "Given the fact that the patient AA-1's tumor tissue expressed high levels of EphA2, it is conceivable that tumor-expression of EphA2 has triggered activation of EphA2-reactive CD8+ precursor cells, of which the majority remained as effector memory and central memory T cells." (PMID 18093336, 2007). "Expression of IL-13Rα 2 and EphA2 in the patient AA-1's tumor led us to address whether antigen-specific T cell response had been mounted in this patient." (PMID 18093336, 2007). "We examined whether vaccinations with synthetic mouse EphA2 (mEphA2)-derived peptides that serve as T cell epitopes could induce protective and therapeutic anti-tumor immunity." (PMID 15563374, 2004). "These published observations suggest that immunological targeting of EphA2 may also inhibit tumor growth by suppression of tumor-neoangiogenesis." (PMID 15563374, 2004). "Soluble EphA2-Fc or EphA3-Fc receptors inhibit angiogenesis and tumor formation in multiple models." (PMID 15563374, 2004). "Further studies have shown that soluble EphA2-Fc and EphA3-Fc receptor constructs inhibit tumour angiogenesis and growth in vivo, providing the first functional evidence for EphA receptor regulation of tumour angiogenesis." (PMID 12865906, 2003). "Notably, CD4+ T cells were increased in the EphA2-overexpressing tumor-bearing lungs." (PMID 40867322, 2025). "In addition, EphA2 overexpression has been associated with resistance to multiple EGFR-targeted TKIs in other malignancies, where EphA2 blockade with ALW-II-41-27 reversed acquired resistance and re-sensitized tumor cells to erlotinib and afatinib." (PMID 41440001, 2025).